ASNS (asparagine synthetase (glutamine-hydrolyzing))
Diseases named in the same sentence as ASNS in open-access papers (continued):
Sharing a sentence is not in itself a finding about the gene and the disease.
melanoma (8 papers, 2015 to 2025). A malignant, usually aggressive tumor composed of atypical, neoplastic melanocytes. "L-ASNase effectiveness in melanoma cells was noted to be limited by the upregulation of ASNS, which some tumor cells utilize to counteract asparagine deprivation." (PMID 41459545, 2025). "ASNS knockdown hinders growth of melanoma cells and epidermoid carcinoma cells, inducing cell cycle, down-regulation of CDK4, CDK6, and Cyclin D1, and induction of p21WAF." (PMID 31998641, 2019). "Furthermore, a previous study reports that knockdown of ASNS by lentivirus-mediated RNA interference inhibits cell growth in epidermoid carcinoma cells and melanoma cells." (PMID 34540668, 2021). "Indeed, ASNS silencing in melanoma and colon carcinoma cells causes the activation of the MAPK cascade and the activation of mTORC1 that, in turn, potentiates ATF4-dependent ASNS induction." (PMID 31998641, 2019). "Knockdown of ASNS suppresses cell growth in human melanoma cells and epidermoid carcinoma cells." (PMID 28629319, 2017). "Similarly, ASNS silencing in melanoma cells was recently reported to result in cell cycle arrest." (PMID 26499495, 2015). "After ASNS knockout, the cyclin‐dependent kinase (CDK4), cyclin‐dependent kinase (CDK6), and cyclin D1 significantly downregulated in melanoma cells, which decreased cell proliferation." (PMID 39210809, 2024).
microcephaly (8 papers, 2016 to 2023). A congenital or acquired developmental disorder in which the circumference of the head is smaller than normal for the person's age and sex. "Asparagine Synthetase Deficiency (ASNSD) is a disease that results from biallelic mutations in the ASNS gene and presents with congenital microcephaly, intractable seizures, and progressive brain atrophy." (PMID 37111157, 2023). "The mutations (A6E and F362V) lead to destabilization of theprotein, and thus the protein expression is significantly reduced, suggestingthat loss of ASNS protein is the cause of microcephaly." (PMID 35057642, 2023). "Mutations in asparagine synthetase (ASNS), which converts glutamine to glutamatealong with the conversion of aspartate to asparagine, cause microcephaly inhuman (Ruzzo and others2013)." (PMID 35057642, 2023). "For example, mutations in ASNS, which encodes asparagine synthetase, have also been identified in patients characterized by congenital microcephaly, intellectual disability, progressive cerebral atrophy and intractable seizures." (PMID 35069108, 2021). "The authors discovered that recessive mutations in ASNS are responsible for a severe neurological phenotype characterized by congenital or progressive microcephaly and developmental delay." (PMID 31123592, 2019). "We here report two novel mutations in ASNS in a German family with two girls suffering from microcephaly, which are inherited in a compound heterozygous manner in the family." (PMID 30057589, 2018). "In conclusion, we here present two novel mutations in ASNS identified in a family with two children with microcephaly." (PMID 30057589, 2018). "Mutations in ASNS have recently been identified as the cause of microcephaly and severe defects in brain development in human patients." (PMID 30057589, 2018). "In this context, it has been reported that recessive loss-of-function mutations of ASNS in patients caused congenital microcephaly, intellectual disability and progressive cerebral atrophy." (PMID 27188386, 2017). "We report two novel mutations in the ASNS gene in two Saudi patients from first cousin marriages who presented with congenital microcephaly, hyperekplexia, cerebral atrophy, simplified gyral pattern, and hypoplastic cerebellum and pons." (PMID 27422383, 2016). "However, while the association of ASNS mutations and microcephaly is now well-established, the pathophysiology of these mutations is still unclear." (PMID 30057589, 2018). "The novel variants expand the growing list of microcephaly causing mutations in ASNS." (PMID 30057589, 2018). "Secondly, how does a reduced activity of ASNS result in microcephaly?" (PMID 30057589, 2018).
colorectal cancer (7 papers, 2019 to 2024). A primary or metastatic malignant neoplasm that affects the colon or rectum. "For example, the ASNS gene has been found to be mutated in human colonic epithelial cells and suggested to be implicated in the initiation of colorectal cancer." (PMID 34540668, 2021). "Subsequent data have confirmed that the mRNA and protein levels of ASNS in colorectal cancer cells treated with STM2457 were significantly downregulated." (PMID 39132158, 2024). "Compared with normal tissues adjacent to cancer, ASNS is highly expressed in colorectal cancer tissues of CRC patients." (PMID 39132158, 2024). "For example, in KRAS-mutant colorectal cancer cells, the high expression of ASNS induced by PI3K-AKT-mTOR pathways leads to metabolic shifts that sustain tumor growth." (PMID 38474084, 2024). "Therefore, we identified SLC2A3 and ASNS as critical ferroptosis genes for JAT inhibition in colorectal cancer." (PMID 37710311, 2023). "In colorectal cancer ASNS expression may also have pro-tumor or anti-tumor roles." (PMID 31998641, 2019).
liver cancer (7 papers, 2021 to 2025). An epithelial or non-epithelial malignant neoplasm that arises from the liver. "The study showed that the mutated asparagine synthetase (ASNS) hypermethylation can cause gastric as well as hepatic cancers to sensitized asparaginase therapy." (PMID 34900668, 2021). "To investigate the mechanism by which ASNase reduces cell viability and induces cell death of liver cancer cells, we examined expression levels of GS and ASNS." (PMID 34796113, 2021). "Immunoblotting confirmed loss of ARG1 and AGMAT and increased levels of RBM39 and ASNS in tumors of liver cancer patients compared to adjacent non-tumor tissue." (PMID 37804830, 2023). "Moreover, arginine levels were decreased in non-tumor tissues upon Asns knockdown but elevated in tumor tissues, again supporting the notion that ASNS is critical for tumor formation by promoting arginine uptake into liver cancer cells." (PMID 37804830, 2023). "Consistent with our recent findings in pediatric liver cancer, we also observed that CM272 markedly reduced the expression of amino acid metabolic enzymes (ASNS, PYCR1, BCAT2), as well as genes involved in the serine pathway (PHGDH, PSPH, PSAT1)." (PMID 39810240, 2025).
hepatocellular carcinoma (6 papers, 2013 to 2025). A malignant tumor that arises from hepatocytes. "Moreover, it has been found that the expression of ASNS is associated with the prognosis of patients with hepatocellular carcinoma and ASNS expression is also correlated with the aggressiveness of glioma." (PMID 34540668, 2021). "The expression of ASNS is also an independent predictor of postoperative survival of hepatocellular carcinoma." (PMID 35681277, 2023). "ASNS expression has also been shown to be anindependent factor affecting survival in hepatocellular carcinoma and low ASNSlevels are correlated with poorer surgical outcomes." (PMID 31188922, 2019). "Research has shown that upregulation of PTTG1 expression promotes transcriptional activation of asparagine synthetase (ASNS), a key activator of Asn metabolism, enhancing Asn metabolism and activating mTOR pathway to promote progression of hepatocellular carcinoma." (PMID 40028341, 2025).
colon carcinoma (4 papers, 2019 to 2024). "ASNS has been found up-regulated in several human cell lines and clinical specimens derived from colon carcinoma with mutated KRAS." (PMID 31998641, 2019). "We have already confirmed that ASNS and CEBPA expression were associated with lymph node metastasis in colon cancer patients." (PMID 35174151, 2022). "KRAS-mediated overexpression of ASNS has been also described in colon cancer in the context of adaptation to nutritional stress upon Gln starvation." (PMID 31998641, 2019). "Moreover, ASNS knockdown in vivo suppressed the growth of KRAS-mutant colon cancers, suggesting a tumor-favoring role of the enzyme in these cancers." (PMID 31998641, 2019). "The low expression of ASNS and CEBPA in colon cancer tissues was closely related to the occurrence of lymph node metastasis, which had an impact on prognosis and shortened OS (Freeman., 2013)." (PMID 35174151, 2022). "It was found that in our cluster model, ASNS and CEBPA play an important role in the prognosis of colon cancer patients, and patients with low ASNS and CEBPA expression had a worse prognosis, i.e., more prone to lymph node metastasis." (PMID 35174151, 2022). "We further examined the expression of ASNS, CEBPA, and CAD in tumor tissues and adjacent normal tissues from different colon cancer patients." (PMID 35174151, 2022). "In this study, three key genes, ASNS, CEBPA, and CAD, were screened by Cox regression analysis in colon cancer." (PMID 35174151, 2022). "Based on the expression profiles of ASNS, CEBPA, and CAD, 415 TCGA colon cancer samples were analyzed by consistent clustering and tSNE algorithm, and the samples were divided into two clusters, Cluster 1 and Cluster 2, with longer and shorter survival time, respectively." (PMID 35174151, 2022). "Moreover, both ASNS knock-down and the combined treatment with rapamycin and ASNase inhibited the growth of KRAS-mutant colon cancer xenografts in vivo." (PMID 31998641, 2019).
epidermoid carcinoma (4 papers, 2017 to 2024). "The loss of function of asparagine synthetase (ASNS) resulted in the suppression of cell proliferation and inhibition of tumor growth in human gastric cancer cells, melanoma cells, and epidermoid carcinoma cells." (PMID 32279073, 2020).
gastric cancer (4 papers, 2018 to 2025). A primary or metastatic malignant neoplasm involving the stomach. "In addition, we noted that some genes (such as CYP1A1, STC2, ASNS, etc.)listed in association with the tumour cell survival, cell proliferation, and cell death also affect the survival of gastric cancer patients under adjuvant chemotherapy." (PMID 30380689, 2018).
glioma (4 papers, 2019 to 2025). A benign or malignant brain and spinal cord tumor that arises from glial cells (astrocytes, oligodendrocytes, ependymal cells). "Clinically, ASNS expression was shown to correlate with an advanced tumor grade and poor prognosis in patients with solid tumors (e.g., glioma) and blood cancers (e.g., ALL)." (PMID 31681605, 2019). "In addition, higher expression of OGT, FOXC1, ASNS, GPT2, CBS, or FTH1 was also associated with poorer outcomes in clinical cases with renal clear cell carcinoma or glioma." (PMID 40416363, 2025). "Additionally, overexpression of ASNS has been reported to be correlated with enhanced aggressiveness in glioma." (PMID 34540668, 2021).
Intellectual disability (4 papers, 2016 to 2022). "ASNS-deficiency leads to progressive cerebral atrophy and intellectual disability and can cause severe neurological impairment without involvement of peripheral tissues." (PMID 27538496, 2016). "Several of the cerebellar specific protein alterations are associated with neurological diseases including epilepsy and intellectual disability including BRAF, CRMP5 and ASNS." (PMID 35264729, 2022).
sarcoma (4 papers, 2019 to 2025). A usually aggressive malignant neoplasm of the soft tissue or bone. "In this screen, the strongest inhibitory effect on sarcoma growth was produced by silencing of asparagine synthetase (ASNS), which established that adequate asparagine availability was a metabolic vulnerability with potential anti-sarcoma therapeutic value." (PMID 32898143, 2020). "Ectopic expression of either variant in ASNS-null Jensen rat sarcoma (JRS) cells did not support proliferation in the absence of medium-supplied asparagine, whereas expression of wild-type enzyme completely restored growth." (PMID 36613999, 2022).
Acute myeloblastic leukemia (3 papers, 2015 to 2022). "Expression of ASNS is also correlated with drug resistance in childhood acute lymphoblastic leukemia (cALL) and some forms of acute myeloblastic leukemia (AML), which are typically deficient in their ability to synthesize asparagine de novo." (PMID 25621173, 2015).
lymphoma (3 papers, 2019 to 2021). A malignant (clonal) proliferation of B- lymphocytes or T- lymphocytes which involves the lymph nodes, bone marrow and/or extranodal sites. "Moreover, the strict requirement for extracellular Asn of ALL blasts (and of some lymphoma models), due to low levels of ASNS protein expression, was the first example of a cancer-specific auxotrophy for a non-essential amino acid." (PMID 31998641, 2019).
ASNS Deficiency (2 papers, 2023 to 2024). "Biallelic mutations in the ASNS gene result in ASNS Deficiency (ASNSD)." (PMID 36873094, 2023).
brain tumors (2 papers, 2017 to 2025). "Differential expression of ASNS in ependymomas and certain types of medulloblastomas also supports asparaginase testing against these pediatric brain tumors." (PMID 28245795, 2017). "In ex vivo microenvironmental co-culture, ASNS knockdown abrogated the capacity of SCLC cells to adapt to nutrient restriction, ROS challenge, and stromal crosstalk—paralleling auto- and paracrine metabolic adaptations described in breast and brain tumors." (PMID 41463097, 2025).
chordoma (2 papers, 2021 to 2023). Chordomas are rare malignant tumors arising from embryonic remnants of the notochord in axial skeleton. "(2021) utilized LC-MS/MS to identify the enzyme asparagine synthetase (ASNS) as a novel prognostic biomarker of recurrence in chordoma of the skull base." (PMID 37197427, 2023). "In a functional experiment to evaluate the impact ASNS in oncogenesis, knockdown of ASNS in chordoma cells (UM-Chorl and MUG-Chor1) by siRNA resulted in inhibition of cell growth, colony formation, migration and invasion." (PMID 37197427, 2023). "CCK-8 assay, clonal formation assay and transwell assay were used to test the effect of asparagine synthetase (ASNS) on the proliferation, migration and invasion in chordoma cell lines." (PMID 34540668, 2021). "Knockdown of ASNS by small interfering RNA (siRNA) inhibited the growth, colony formation, migration and invasion of chordoma cells in vitro." (PMID 34540668, 2021). "Until now, there has been no study of ASNS expression in chordoma." (PMID 34540668, 2021).
colorectal tumor (2 papers, 2022 to 2024). "Consistent with this, using The Cancer Genome Atlas (TCGA) we found that ASNS expression was significantly elevated in human colorectal tumour (2.64-fold) and metastatic (2.22-fold) tissue in comparison to normal." (PMID 39332495, 2024).
diabetes (2 papers, 2020 to 2024). "The combined cellular and biochemical results thus suggest ASNS inhibition is a possible mechanism underlying the low asparagine levels in alcoholism and diabetes." (PMID 38362406, 2024). "The regulation of diabetes is caused by genes including ASNS, CAD, GMPS, and PHGDH." (PMID 33490239, 2020).
lymph node metastases (2 papers, 2022). "Clinical specimen results confirmed that the risk model established was effective, and the different expression pattern of ASNS and CEBPA was correlated with TNM stage and lymph node metastasis, whilst that of CAD was correlated with post-operative tumor metastasis and recurrence." (PMID 35174151, 2022).
rectal cancer (2 papers, 2020 to 2025). A primary or metastatic malignant neoplasm that affects the rectum. "Furthermore, ASNS deficiency was associated with reduced treatment response and worse survival in rectal cancer patients treated with neoadjuvant chemoradiotherapy." (PMID 39796613, 2025).
acute leukemia (1 paper, 2021). A clonal (malignant) hematopoietic disorder with an acute onset, affecting the bone marrow and the peripheral blood. "Importantly, acute leukemia cells are auxotrophic for Asn because they express low levels of ASNS, and this phenotype leads to high sensitivity to asparaginase." (PMID 34445444, 2021). "However, ASNS expression is not the only factor that contributes to ASNase response, and other mechanisms need to be further elucidated to improve prognosis in acute leukemia patients." (PMID 34445444, 2021).
adenoma (1 paper, 2024). A neoplasm arising from the epithelium. "Loss of ASNS blocks proliferation in late-stage cells, attenuating mTORC1 signalling and ATP production, whereas early adenoma cells are largely resistant to ASNS knockdown due to their ability to sense ASN levels and source it through autophagy." (PMID 39332495, 2024). "We show that loss of asparagine synthetase (ASNS) blocks their proliferation, whereas early adenoma cells are largely resistant to ASN deprivation." (PMID 39332495, 2024).
adenovirus infection (1 paper, 2023). "Moreover, adenovirus infection upregulated expression of ASNS in infected cells, whereas knockdown of ASNS severely impaired viral replication." (PMID 37065159, 2023).
Allergy (1 paper, 2023). An allergy is an immune response or reaction to substances that are usually not harmful. "Neither ASNS- or GRIA1- analyzed variants nor ancestry were significantly associated with L-ASP allergy." (PMID 38044950, 2023).
B cell lymphomas (1 paper, 2022). "Using [U-13C5]-l-glutamine in vitro and in vivo in a mouse model of B cell lymphomas (BCLs), we demonstrated that supraphysiological or physiological concentrations of asparagine prevent de novo asparagine biosynthesis, regardless of ASNS expression levels." (PMID 35857457, 2022).
bladder cancer (1 paper, 2025). "Further Kaplan-Meier analysis revealed that high expression of ASNS was associated with poor overall survival for patients with bladder cancer." (PMID 39964752, 2025). "Clinically, ASNS is upregulated and is associated with a poor response to immunotherapy in bladder cancer." (PMID 39964752, 2025). "However, further research should focus on the underlying mechanisms of ASNS upregulation in bladder cancer, which may help to advance understanding its special role." (PMID 39964752, 2025). "To further explore the profiles of ASNS in bladder cancer, we mined the TCGA dataset and found that the mRNA level of ASNS was significantly upregulated in bladder cancer." (PMID 39964752, 2025). "Moreover, IHC staining in bladder cancer tissue array show that the expression of ASNS was upregulated in tumor tissues." (PMID 39964752, 2025). "Collectively, these findings reveal that ASNS inhibition could activate RIG-I–induced IFN-β signaling in bladder cancer." (PMID 39964752, 2025). "To further investigate whether IFN-β signaling is essential for ASNS inhibition–elicited antitumor immunity, we genetically abrogated IFN-β production in bladder cancer cells, which completely reversed ASNS deficiency–mediated inhibition of tumor growth in vivo." (PMID 39964752, 2025).
chronic hepatitis B (1 paper, 2017). "We then examined the mRNA levels of ASNS and ATF6 in 90 HCC patients, 77 chronic hepatitis B patients and 70 controls." (PMID 28629319, 2017).
congenital microcephaly (1 paper, 2018). "Within ASNS, which has previously been associated with congenital microcephaly, two new mutations were identified: c.1165G > C, p.E389Q and c.601delA, p.M201Wfs∗28 (all positions in the ASNS gene are annotated to RefSeq NM_133436.3, Ensembl ENST00000394309.3, GRCh37)." (PMID 30057589, 2018).
cystic kidneys (1 paper, 2024). "Our previous metabolomic analysis of KspCre;Pkd1ΔC/flox cystic kidneys in newborn mice highlighted an impairment in the aminoacyl-tRNA pathway as well as an imbalance in amino acid biosynthesis, suggesting that the amino acid response (AAR) could be the driver for ASNS upregulation in PKD." (PMID 38684863, 2024).